FUT4 (fucosyltransferase 4)
Diseases named in the same sentence as FUT4 in open-access papers (continued):
Sharing a sentence is not in itself a finding about the gene and the disease.
osteoarthritis (3 papers, 2013 to 2023). A noninflammatory degenerative joint disease occurring chiefly in older persons, characterized by degeneration of the articular cartilage, hypertrophy of bone at the margins and changes in the synovial membrane. "Moreover, FUT4 significantly modulated NF-κB pathway and affected the progression of osteoarthritis." (PMID 37946130, 2023).
Miscarriage (2 papers, 2021 to 2023). A pregnancy that ends at a stage in which the fetus is incapable of surviving on its own, defined as the spontaneous loss of a fetus before the 22th week of pregnancy. "The general α1,3-fucosylation state, especially LeY and FUT4 may serve as the potential new diagnostic biomarkers and therapeutic targets for miscarriage patients." (PMID 37798282, 2023). "Our studies suggest that lower FUT4 may hampers trophoblast proliferation, migration and invasion ability, which is one of the critical causes for miscarriage, by decreasing LeY biosynthesis." (PMID 37798282, 2023). "Among these α1,3 FUTs, FUT4 was decreased significantly in the trophoblast tissues of miscarriage patients, as examined by Real-time PCR and western blot." (PMID 37798282, 2023). "All these findings suggest that the overall level of protein α1,3-fucosylation (fucosylated glycans, key enzyme FUT4, especially difucosylated LeY oligosaccharide) was reduced in trophoblast from miscarriage patients." (PMID 37798282, 2023). "We revealed that decreased α1,3-fucosylation, especially LeY oligosaccharide and FUT4 on the trophoblast of miscarriage patients in comparison with early normal pregnancy women." (PMID 37798282, 2023). "In addition, similar alteration of α1,3-fucosylation, FUT4 and LeY in serum were also detected in the pregnancy women and miscarriage patients." (PMID 37798282, 2023).
fatty liver (1 paper, 2025). "Furthermore, based on network pharmacology predictions, molecular docking studies suggested that the primary targets of Catechin gallate in alleviating fatty liver might include ABCB1, DYRK1A, PGD, and FUT4." (PMID 40699724, 2025).
fatty liver disease (1 paper, 2025). A reversible condition wherein large vacuoles of triglyceride fat accumulate in liver cells via the process of steatosis. "In this study, through network pharmacology and molecular docking, we identified potential targets for Catechin gallate in the treatment of fatty liver disease, which include ABCB1, DYRK1A, PGD, and FUT4." (PMID 40699724, 2025).
male infertility (1 paper, 2021). The inability of the male to effect fertilization of an ovum after a specified period of unprotected intercourse. "The differences in serum CLU and FUT4 concentrations, and in the expression of core fucose and antennary fucose α1,2-linked in CLU glycans between the N group and other groups examined suggest that the disturbances in sperm count, motility, and morphology are not the only cause of male infertility." (PMID 34341430, 2021).
metastatic cancer (1 paper, 2019). A carcinoma which has spread from the original site of growth to another anatomic site. "Knockdown of FUT4 and FUT7 in metastatic cancer cells prevented disruption of an in vitro BBB model." (PMID 31104223, 2019).
oral carcinoma (1 paper, 2021). "In this study, we examined the mRNA expressions of fucosidase (FUCA1) and FUTs (FUTs (FUT3, FUT4, FUT5, FUT6, FUT8) in human oral cancer tissues." (PMID 34703796, 2021). "Increased FUT4 and FUT5 levels were also observed in tongue carcinoma which is a more aggressive form of oral cancer, and also in the patients having tobacco consumption habit." (PMID 34703796, 2021). "Therefore, the present investigation was aimed to evaluate the clinical significance of mRNA expressions of various fucosyltransferses (FUT3, FUT4, FUT5, FUT6, FUT8) and fucosidases (FUCA1) in oral cancer progression." (PMID 34703796, 2021). "Collectively, results suggest that elevated mRNA levels of FUT4, FUT5 and FUT8 may be used as worst prognostic indicators for oral carcinoma." (PMID 34703796, 2021).
rectal cancer (1 paper, 2022). A primary or metastatic malignant neoplasm that affects the rectum. "To reveal the distinct role of FUT4 in rectal cancer, we analyzed FUT4-mediated function in the rectal cancer-specific genes (upregulated) group." (PMID 36164349, 2022). "In rectal cancer, FUT4 predicts the outcome of patients through an immune macroenvironment-mediated mechanism." (PMID 36164349, 2022). "According to the results of the enrichment analysis of rectal cancer-specific genes, FUT4 exerts its regulating impact by upregulating the immune response." (PMID 36164349, 2022). "The present results demonstrated the rectal cancer-specific regulatory role of FUT4 and revealed its specific regulatory mechanism in colon and rectal cancers." (PMID 36164349, 2022). "The results of the enrichment analysis showed that FUT4 positively regulates the immune system process in patients with rectal cancer." (PMID 36164349, 2022). "According to the findings, FUT4 participated in the “positive regulation of immune system process” and “glycoprotein biosynthetic process” in rectal cancer." (PMID 36164349, 2022). "The results of this study propose two potential genes as target candidates for the precise treatment of rectal cancer: the immune microenvironment regulatory gene FUT4 and kinase family member CHEK2." (PMID 36164349, 2022). "To further investigate the potential role of FUT4 in colon and rectal cancers, we detected its co-expression genes and performed functional enrichment analysis." (PMID 36164349, 2022). "Collectively, these results indicated that FUT4 decreases the level of infiltration of M2 macrophages to predict the outcome of patients with rectal cancer and induce a more active immune response in rectal cancer." (PMID 36164349, 2022). "This suggests that CHEK2 may be a core regulatory kinase in rectal cancer, exerting its biological effect by regulating the expression of FUT4 co-expression genes." (PMID 36164349, 2022). "Then multiplatforms were applied to analyze the rectal cancer-specific core regulatory gene FUT4's mediated immune microenvironment, network of co-expression genes, clinic feature's stratified expression status, and mediated function in order to roundly describe the role of FUT4 in rectal cancer." (PMID 36164349, 2022). "Thus, based on the results of the enrichment analysis, we hypothesized that FUT4 plays a regulatory role in outcome in patients with rectal cancer by targeting immune-related processes and contributing to the tumor immune microenvironment." (PMID 36164349, 2022). "The complex role of FUT4 in CRC may be due to the investigation of both colon and rectal cancers in this study." (PMID 36164349, 2022).
teratozoospermia (1 paper, 2021). "The comparison the seminal plasma FUT4 concentrations between study groups indicates that spermatozoa morphology abnormalities characteristic for teratozoospermia are associated with decreased FUT4 concentration." (PMID 34341430, 2021).
tongue cancer (1 paper, 2021). A malignant neoplasm affecting the tongue. "Analyzing the mRNA expression of FUTs and FUCA1 revealed that, mRNA levels of FUTs and FUCA1 were higher with significant up regulation of FUT4 and FUT8 in the tongue carcinoma patients as compared to the buccal carcinoma as a primary site of the disease." (PMID 34703796, 2021). "Further, we have documented that the treatment of tobacco metabolites such as 4-NQO, NNK, Benzopyrene lead to the increase in FUT4, FUT5, FUT6, and FUCA1 transcripts in a dose dependent manner in treated tongue carcinoma cells." (PMID 34703796, 2021). "There was a significant up regulation of FUT3, FUT4, FUT5, and FUT8 (P = 0.019, 0.025, 0.087, and 0.034, respectively) in patients with tongue carcinoma in comparison with patients with buccal carcinoma as a primary site." (PMID 34703796, 2021).
Trichiasis (1 paper, 2019). Inversion and rubbing of the eyelashes against the globe of the eye. "The upregulation of pro-inflammatory mediators and cell markers (CCL2, CCL3, CXCL5,IL1B, IL6, CHUK, FUT4 andPTPRC) is indicative of higher levels of inflammation and leukocyte infiltration in the conjunctival tissue of patients who developed ECA following trichiasis surgery." (PMID 37426632, 2019).
tumor (314 papers, 2002 to 2026). "Our study has identified, in addition to systemic levels of testosterone, tumor-specific AR and its fucosylation signaling effectors (FUT4, fucosylated-L1CAM, and AJs), as potential risk factors for disease progression and as promising prognostic biomarkers." (PMID 38326303, 2024). "In our study, we found that high expression of FUT4 mRNA in PTC from the TCGA database was associated with a high level of tumor infiltration both for immune and stromal cells as exhibited by ESTIMATE analysis." (PMID 32486143, 2020). "Many previous studies reported that FUT4 gene expression is associated with pro-tumorigenic function, such as tumor growth and invasion, and drug resistance." (PMID 32486143, 2020). "Consistent with pro-tumorigenic function, loss of FUT4 in melanoma cells inhibits proliferation and tumor growth and is associated with reduced EGFR and MAPK signaling." (PMID 31450600, 2019). "FUT4 catalyzes the transfer of the Fuc of GDP-Fuc to the N-acetylglucosamine of the sugar chain, and FUT4 is a key enzyme in the synthesis of the tumor-associated carbohydrate antigen LeY." (PMID 28423676, 2017). "Tumors displaying CD15/FUT4-high expression pattern were more frequently associated with advanced tumor stage III and IV and with lower-densities of CD3+ and CD8+ T cells peritumoral infiltrate, confirming the data obtained on the first series." (PMID 26427914, 2015). "Our findings support the concept that androgen/AR reduces global fucosylation levels by transcriptionally downregulating FUK while tilting its function toward tumor promotion by upregulating FUT4 expression." (PMID 38326303, 2024). "Our data showed that FUT3 was upregulated from the early stage, while FUT4 progressively increased with the tumor stage, suggesting a linkage conversion of α-fucosylation as the tumor progresses." (PMID 37168374, 2023). "Autophagic tumor-associated macrophages have been found to promote TGF-β1 secretion and EMT in LUAD through the FUT4/p-ezrin pathway." (PMID 37256139, 2023). "According to the analysis conducted using TIMER2.0, the expression of FUT4 is significantly correlated with infiltration of multiple types of immune cells in the tumor immune microenvironment." (PMID 36164349, 2022). "Although the function of FUT9 in tumors not perfectly clear, a previous study showed that suppression of its two gene family orthologs, FUT1 and FUT4, greatly impeded the tumor development, suggesting a potential oncogenic role of this gene." (PMID 35939448, 2022). "In a variety of tumor cells, overexpression of FUT4 is attributed to their increased proliferation rate, decreased susceptibility to apoptosis as well as increased adhesiveness, invasiveness and metastasis, and is generally related to a poor prognosis." (PMID 36233470, 2022). "For this, we evaluated the general expression of fucosylation-related genes detected in tumour cells using gene sets associated with the GDP-Fuc synthesis (GMDS, TSTA3), fucosyltransferases (FUT2, FUT3, FUT4, FUT6) or both." (PMID 35017635, 2022). "The integrated results suggested that the FUT4 co-expression genes perform their regulatory function by exerting a broad effect on nuclear activity and gene translation in tumor cells." (PMID 36164349, 2022). "On the contrary, FUT4 expression in tumor tissues that had been infected with miR-317b-5b-loaded engineered exosomes was lower than that in control group (P < 0.05)." (PMID 34671604, 2021). "In contrast, FUT4-overexpressing PTCs were associated with up-regulation of CTLA-4, PD-1, and PD-L1 in the tumor microenvironment that is known to exert immunosuppressive and pro-tumorigenic activities." (PMID 32486143, 2020).
tumor (continued). "Oncomine and TCGA database also revealed the increased FUT4 expression in CRC tumor tissues compared with normal tissues." (PMID 32209115, 2020). "In tumor tissue, overexpression of fut4 transferring GDP-fucose to the Lewis Y antibody terminal N-GlcNac with the 1,3-linkage, which promoting neoplastic cell proliferation." (PMID 32596162, 2020). "It is possible that opposing tumorigenic vs. tumor-suppressive functions of FUT4 are elicited in stage- and context-specific manners." (PMID 31450600, 2019). "FUT4 is upregulated in several cancer types and has been shown to promote proliferation, invasion, tumor growth, and drug resistance." (PMID 31450600, 2019). "As ERKs and JAK/STAT5 cascades have been implicated in immune evasion, we analyzed tumor-infiltrating immune cell subpopulations in relation to gene expression levels of LY6G6D, FUT4 and others key immune modulatory molecules." (PMID 30670049, 2019). "Based on the inhibitory role of miR-200b in tumorigenesis in vitro, we explored the suppression effect of miR-200b on tumor growth and metastasis in vivo, as well as its impact on the expression of FUT4 in xenografts." (PMID 28692034, 2017). "We observed that miR-200b greatly impeded tumor growth, whereas FUT4 cDNA significantly promoted tumor growth in tumor volume and mass at the end point, compared with the control group." (PMID 28692034, 2017). "IHC staining also showed the regulatory role of FUT4 shRNA on the expression of FUT4 and Ki67 in the tumor tissues." (PMID 28640257, 2017). "FUT4 catalyzes the transfer of the Fuc of GDP-Fuc to the N-acetylglucosamine of sugar chain, and it is a key enzyme in the synthesis of tumor associated carbohydrate antigen Lewis Y (LeY)." (PMID 26636541, 2016). "FUT4 is highly expressed in a variety of cancers, including stomach cancer, pancreatic cancer, colon cancer and ovarian cancer, is closely correlated to tumor proliferation, apoptosis, metastasis and EMT." (PMID 26636541, 2016). "CD15/FUT4 transcript was significantly higher in tumor tissues than normal control in TCGA series comprising 210 CRCs and 22 and normal colorectal mucosa specimens, respectively." (PMID 26427914, 2015). "CD15/FUT4 overexpression is driven by constitutive oncogenic signalling pathways in the tumor cells (innate immune resistance) acting as a novel RAF-MEK-ERK kinase downstream regulator through ERBB3 or FGFR4 activation, respectively." (PMID 26427914, 2015). "Among the 32 tumors of the discovery set, 23 (72 %) of CD15/FUT4-positive tumors were classified as low or high and had a higher recurrence than other tumor-related immune antigen i.e., CD68, CD73." (PMID 26427914, 2015). "Each treatment group was analyzed clinically (tumor volume, tumor weight and body weight) and each treatment on FUT4 expression was determined by western blotting and immunohistochemical staining." (PMID 25672851, 2015). "Of note, expression of CD15/FUT4 on the surface of tumor cells indicated a good concordance with transcript levels." (PMID 26427914, 2015). "In conclusion, Rg3 induces tumor cell apoptosis correlated with its inhibitory effect on NF-κB signaling pathway-mediated FUT4 expression." (PMID 26094873, 2015). "Additionally, Fucosyltransferase 4 (FUT4) promotes cancer progression by enhancing tumor proliferation and migration." (PMID 40699724, 2025). "Interestingly, FUT3 was highly expressed from early-stage cancer, whereas FUT4 gradually increased with tumor progression." (PMID 37168374, 2023). "Genes PRKCZ (Protein Kinase C Zeta), FGR (Src family protein), KDM4B, MPO, COL11A1, FUT4 (Fucosyltransferase IV), and APEH (acylpeptide hydrolase) are directly associated with tumor aggressiveness, growth, and migration, and invasiveness, resulting in poor clinical outcome in cancer patients." (PMID 38086861, 2023).
tumor (continued). "Additionally, the fucosyltransferase 4 (FUT4) is a crucial enzyme in post-translational modification of cell-surface proteins involved in various pathological conditions such as tumor multidrug resistance (MDR)." (PMID 35281907, 2022). "To clarify whether the FUT4 gene attenuates chemosensitivity in tumor cells, we constructed FUT4siRNA and evaluated its effects on cisplatin-induced apoptosis and cell growth inhibition." (PMID 32948132, 2020). "Indeed, knockdown of FUT4 significantly augmented the inhibitory effects of cisplatin on tumor growth." (PMID 32948132, 2020). "Among these, the FUT4 gene plays a critical role in regulating tumor chemosensitivity." (PMID 32948132, 2020). "Therefore, it is critical to find effective drugs which can decrease the synthesis of FUT4/LeY and inhibit tumor growth." (PMID 25672851, 2015). "Upregulation of CD15/FUT4 on the tumor cell surface could represent a potential target to enhance antitumor effector functions in the tumor microenvironment." (PMID 26427914, 2015). "Similarly, FUT4 overexpression has been linked to increased cell proliferation, migration, invasion, and resistance to apoptosis, and FUT7 overexpression has demonstrated comparable tumor-promoting features." (PMID 40252176, 2025). "As an example, the suppression of the expression of fucosyltransferases FUT1 and FUT4 reduces the synthesis of Ley, which is expressed at the cell surface and involved in several physiological and pathological processes, and it results in inhibition of tumor development." (PMID 35943155, 2022). "Therefore, it will require further investigation to see whether the FUT4-overexpressing PTCs activate EMT or represent those with a high level of tumor-infiltrating stromal cells and low tumor purity." (PMID 32486143, 2020). "However, FUT4 has been reported to elicit anti-tumor effects." (PMID 31450600, 2019). "Moreover, FUT4 stimulates epithelial-mesenchymal transition (EMT) to promote tumor metastasis." (PMID 26094873, 2015). "However, whether Rg3-induced inhibition on tumor development involves reduced NF-κB signaling and FUT4 expression remains unknown." (PMID 26094873, 2015). "ST analysis showed widespread NETs distribution in tumor tissues, with NETs-related markers S100A8, FUT4, LCN2, S100A9, and HSP3A exhibiting high expression across tissue regions." (PMID 41488283, 2026). "Focusing on glycosyltransferases expression in tumor tissues, we observed two distinct expression clusters, segregating FUT3, FUT4, FUT6, and ST3GAL4 transcripts, from FUT7, FUT9, ST3GAL3, and ST3GAL6." (PMID 39508360, 2025). "However, no Fut4 expression which encodes CD15 or Cd177 was detected in our datasets indicating of lack of capture of neutrophils in our scRNA Seq analysis likely due to their fragility during the tumor isolation process." (PMID 38802355, 2024). "Our data demonstrated that tumor tissues contained significantly lower mRNA levels of FUT3 (2.3 fold), FUT4 (2.7 fold), FUT5 (5.9 fold), FUT6 (3.0 fold), FUT8 (2.0 fold), and FUCA1 (2.6 fold) as compared to adjacent normal tissues." (PMID 34703796, 2021). "We found that tumor-infiltrating CD33high cells showed high gene expression levels of CD36, CD14, FUT4 (CD15), CD80, CD86, CSF1R and immune checkpoint ligand genes including CD274 (PD-L1), LGALS9 (galectin-9), PVR and VSIR." (PMID 33000418, 2021). "Since CD15 showed clinical and prognostic significance in PTC based on protein and mRNA expression in the two independent datasets we further addressed the possible relationship between the FUT4 (CD15) mRNA expression and tumor microenvironment in PTC." (PMID 32486143, 2020). "Defining the cancer-specific biosynthetic properties of FUT4 and FUT9 is fundamental for the interpretation of the biological functions that these enzymes exert within a tumor cell." (PMID 30476078, 2019).